IGFBP2 (insulin like growth factor binding protein 2)
Diseases named in the same sentence as IGFBP2 in open-access papers (continued):
Sharing a sentence is not in itself a finding about the gene and the disease.
lung carcinoma (continued). "The sensitivity and specificity of anti-IGFBP-2 autoantibodies in diagnosing lung cancer was 73.2 and 60.6%, respectively." (PMID 23165420, 2013). "The mean plasma concentration of IGFBP2 in lung cancer patients was significantly higher than that in healthy controls (388.12±261.00 ng/ml vs 219.30±172.84 ng/ml, p<0.001)." (PMID 24069370, 2013). "When the tumor size was increasing or the patient was developing metastasis, the serum levels of anti-IGFBP-2 antibodies were increased, suggesting a role for anti-IGFBP-2 antibodies in assessing response to therapy in lung cancer." (PMID 23165420, 2013). "Nevertheless, consistent with the observation in primary tumor tissues, blood IGFBP2 was also increased in a subset of our study’s lung cancer patients." (PMID 24069370, 2013). "At the cut-offs of 1,264.306 and 2,029.312 ng/ml of anti-IGFBP-2 antibodies, the specificity for lung cancer were 60.6 and 89.5%, respectively." (PMID 23165420, 2013). "When serum IGFBP-2 and anti-IGFBP-2 autoantibody were used together in the diagnosis of lung cancer, it can increase the discriminative power for lung cancer with a sensitivity of 85.7% and a specificity of 57.5%." (PMID 23165420, 2013). "A multivariate analysis showed that lung cancer patients whose blood IGFBP2 was higher than 160.9 ng/ml had a poor survival outcome, with a hazard ratio of 8.76 (95% CI 1.12-68.34, p=0.038 after adjustment for tumor size, pathology, and stage)." (PMID 24069370, 2013). "When the data were analyzed on the basis of sex, age, and smoking status, the IGFBP2 values remained significantly higher in lung cancer patients than in controls within each subgroup." (PMID 24069370, 2013). "In conclusion, this study demonstrates that circulating anti-IGFBP-2 autoantibodies can be used as a potential biomarker in diagnosing lung cancer." (PMID 23165420, 2013). "We therefore tested the effects of Igfbp5 and Igfbp2 overexpression on clonogenicity of lung cancer lines." (PMID 22973541, 2012). "Overexpression of the recombinant Igfbp5 and Igfbp2 genes in two lung cancer cell lines significantly inhibited clonogenicity (P < 0.0001)." (PMID 22973541, 2012). "Through in vitro and in vivo experiments, we demonstrated that the upregulation or downregulation of IGFBP2 significantly increased or decreased gefitinib resistance in lung cancer cells, accompanied by the induction of the epithelial-mesenchymal transition (EMT) in these cells." (PMID 38918360, 2024). "Furthermore, the same tendency was observed in lung metastases formed by lung cancer cells with different IGFBP2 levels." (PMID 38918360, 2024). "Similarly, the IGFBP-2 expression level in lung cancer patients was found to be significantly higher than that in controls and associated with an advanced tumor stage." (PMID 36902237, 2023). "Overall the finding provide an insight into the role played by IGFBP2 in lung cancer metastasis." (PMID 37784035, 2023). "Notably, the highest sensitivity (85.7%) of these biomarkers for the diagnosis of lung cancer was seen when the autoantibodies and IGFBP-2 were used in combination." (PMID 35198099, 2022). "In lung cancer cells, IGFBP2 induces erlotinib resistance by activating IGF-1R signaling." (PMID 34349753, 2021). "Interestingly, it showed to reverse chemoresistance in lung cancer cell lines with high expression of IGFBP2, with IGFBP2 being a biomarker of chemoresistance poor outcome in lung cancer patients." (PMID 33761971, 2021). "In pleural effusions, where PAPP‐A is close to 50‐fold elevated as compared to serum, the degradation of IGFBP‐2 remains similar to that in serum 49 and in serum from lung cancer patients the major part of IGFBP‐2 circulates in its free form (data in preparation)." (PMID 29722920, 2018).
lung carcinoma (continued). "In order to test whether there is a significant difference in serum IGFBP2 expression level of lung cancer patients, we compared serum samples of 81 lung cancer patients in training set with 36 age-matched healthy and benign participants." (PMID 29500455, 2018). "Furthermore, serum IGFBP2 levels were correlated with tumor size in lung cancer, and the levels significantly dropped after curative resection in patients with colorectal cancer; both observations implicate serum IGFBP2 as an indicator for tumor burden." (PMID 28036255, 2017). "We recently showed that IGFBP2 is overexpressed in primary lung cancer tissues." (PMID 24069370, 2013). "The finding in this study may provide a potential marker of anti-IGFBP-2 antibody in diagnosing lung cancer." (PMID 23165420, 2013). "The sensitivity of serum anti-IGFBP-2 antibodies in the detection of lung cancer was higher (73.2%) than that of CEA (45.9%), CYFRA21-1 (65.3%), or NSE (50%), (P<0.001, P=0.166 and P<0.001, respectively) although the differences were not significant (P<0.001, P=0.166 and P<0.001, respectively)." (PMID 23165420, 2013). "Characterization of IGFBP2-mediated pathways in lung cancer cells may provide molecular insights into lung cancer progression and potential therapeutic targets for lung cancer patients with increased IGFBP2." (PMID 24069370, 2013). "In the current study, we aimed to evaluate whether serum IGFBP-2 and anti-IGFBP-2 antibody can be used as biomarkers in detection of lung cancer." (PMID 23165420, 2013). "Blood IGFBP2 is significantly increased in lung cancer patients." (PMID 24069370, 2013). "Overexpression of either Igfbp5 or Igfbp2 in two lung cancer cell lines inhibited clonogenicity, suggesting that their upregulation in vivo may protect from tumor predisposition." (PMID 22973541, 2012). "Furthermore, we conducted detection of IGFBP2 protein levels in these 6 lung cancer cell lines." (PMID 38918360, 2024). "The top 10 proteins (MIG6, GAPDH, NDRG1_pT346, BRD4, CD26, TFRC, INPP4B, GSK3ALPHABETA, IGFBP2, and DUSP4) were screened by applying the WBFS algorithm, and they can be regarded as the candidate biomarkers that are most closely associated with the classification of lung cancer subtypes." (PMID 37509950, 2023). "Furthermore, after adjusting for stage, histology, EGFR mutation, age, smoking, and surgery, multivariate analysis revealed that lung cancer patients with greater blood IGFBP2 had a worse survival result, with a hazard ratio of 8.22 (95% CI 1.78–37.92, p = 0.007)." (PMID 38001653, 2023). "Furthermore, multivariate analysis showed that lung cancer patients whose blood IGFBP2 was higher had a poor survival outcome, with a hazard ratio of 8.22 (95%CI 1.78–37.92, P = 0.007) after adjustment for stage, histopathology, EGFR mutation, age, smoking and surgery." (PMID 29500455, 2018). "Nevertheless, IGFBP2 might be significantly increased in a subset of lung cancer patients." (PMID 24069370, 2013). "To test whether there is a difference in circulating IGFBP2 levels between lung cancer patients and healthy controls, we obtained plasma samples of 80 lung cancer patients and 80 case-matched healthy samples from the blood bank maintained at our institution’s department of epidemiology." (PMID 24069370, 2013). "Mechanistically, IGFBP2 stimulated the transcriptional activity of STAT3 on CXCL1, leading to an upregulation of CXCL1 expression in lung cancer cells and subsequently promoting gefitinib resistance." (PMID 38918360, 2024). "In this study, we have demonstrated that the lung cancer cell-monocyte cross-talk modulates the secretion of IFI30, RNH1, CLEC3B, VCAN, IGFBP2, C2 and TUBB4B favoring tumor growth and metastasis." (PMID 37784035, 2023). "In conclusion, this study identifies IFI30, RNH1 and CLEC3B, VCAN, IGFBP2, C2, TUBB4B as the proteins secreted by lung carcinoma cells and monocytes respectively as a result of their mutual interaction." (PMID 37784035, 2023).
lung carcinoma (continued). "Both IGFBP2 and FAK can be used as biomarkers for identifying dasatinib responders among lung cancer patients." (PMID 30609749, 2019). "Mechanistically, IGFBP2 can activate STAT3 to enhance the transcriptional activity of CXCL1, thereby increasing the intracellular expression level of CXCL1, which contributes to the survival of lung cancer cells in the gefitinib environment." (PMID 38918360, 2024). "Previous studies have illustrated that IGFBP2 overexpression facilitates camptothecin resistance via regulating caspase-3 in an IGF-independent manner, and it also promotes EGFR-TKI erlotinib resistance by activating IGF-1R in lung cancer cells." (PMID 38918360, 2024). "Among them, IGFBP2, IGFBP3, IGFBP4, IGFBP6 and IGFBP7 showed higher expression levels, especially in gastric, liver and lung cancer cell lines; conversely, IGFBP1, IGFBP5 and IGFBPL1 showed relatively lower expression, particularly in colorectal, gastric and kidney cancer cell lines." (PMID 37088808, 2023). "One of these trials also measured IGFBP-1 and IGFBP-2 levels, which were concluded to not be significantly related with development of lung cancer in women." (PMID 35198099, 2022). "Patients with lung cancer stage I–II (mean, 1549.671 ng/ml; median, 1651.749 ng/ml) did not have an elevated anti-IGFBP-2 antibodies compared to patients with lung cancer stage III–IV (1667.397 ng/ml; median, 1648.400 ng/ml) (P= 0.548)." (PMID 23165420, 2013). "Our study indicates that the blood IGFBP2 level alone might be not specific or sensitive enough for lung cancer diagnosis because both specificity and sensitivity were about 75%." (PMID 24069370, 2013). "When stratifying lung cancer by tumor stage, the AUC for lung cancer I–II and lung cancer III–IV was 0.656 (95% CI=0.568–0.743; P= 0.001) and 0.685 (95% CI= 0.615–0.755; P<0.001), respectively, indicating some ability of anti-IGFBP-2 antibodies to diagnose lung cancer." (PMID 23165420, 2013). "However, another recent study on 163 patients with different types of cancers, including 34 lung cancer patients, and 13 healthy controls in Germany showed that serum IGFBP2 levels were only significantly elevated in head and neck tumors but not in other types of cancer, including lung cancer." (PMID 24069370, 2013). "The IGFBP2, CTGF, JAG1, and SPARC promoters are most active in the primary culture of human fibroblasts IVP-9TS, while the IGFBP2 and JAG1 promoters virtually are not active in the epithelial cells of the lung cancer Calu-1." (PMID 33804861, 2021).
colorectal cancer (32 papers, 2000 to 2025). A primary or metastatic malignant neoplasm that affects the colon or rectum. "However, our findings still showed an association between IGFBP2 expression and the prognosis in colorectal cancer." (PMID 35546443, 2022). "We conclude that the serum IGF-II and IGFBP-2 profiles may provide insights into underlying biological mechanisms, and that serum IGFBP-2 may have an adjunct role in cancer surveillance in patients with colorectal cancer." (PMID 11044360, 2000). "Lycopene supplementation increases the circulating levels of IGFBP-1 and IGFBP-2 in high-risk populations of colorectal cancer patients, suggesting that lycopene might reduce the risk of colorectal cancer and potentially the risk of other cancers, such as prostate and breast cancer." (PMID 23970935, 2013). "By analyzing 196 chemorefractory colorectal cancer patients with available plasma samples, we showed that high concentrations of IGFBP-1 and/or IGFBP-2 were associated with shorter overall survival." (PMID 38136368, 2023). "Men and women with colorectal cancer, randomly assigned to lycopene capsules for 8 weeks had increased levels of serum IGFBP-2 (by 8.2%, 95% CI: 0.7–15.6% for men and 7.8%, 95% CI: −5.0–20.6% for women)." (PMID 30921005, 2019). "Overexpression of IGFBP2 enhances cell motility and induces liver metastasis in colorectal cancer through the L1 neuronal cell adhesion receptor." (PMID 28977895, 2017). "On the other hand in the case of a manifested colorectal cancer, serum IGFBP-2 levels are significantly elevated and correlate with the stage of disease." (PMID 17118177, 2006). "IGFBP-2 possesses moderately preventing effects on the development of colorectal cancer most likely by antagonizing the effect of serum IGF-II." (PMID 17118177, 2006). "This study investigates four blood-based biomarkers, mSEPT9, IGFBP2, DKK3, and PKM2, for colorectal cancer (CRC) detection." (PMID 39766076, 2024). "The qRT-PCR experiments verified the lower expression of IGFBP2 and IGFBP6 in gastric cancer and the lower expression of IGFBP6 in colorectal cancer." (PMID 37088808, 2023). "We observed in our study the highest IGFBP-1, IGFBP-2 and IGFBP-3 mRNA expression in Dukes’ stage D colorectal cancer cells, having the lowest level IGFBP-6." (PMID 34290976, 2021). "LRG1 has been identified to be differentially expressed in colorectal cancer, and a panel of the CEA, IGFBP2, MAPRE1, and LRG1 proteins is potentially a prediagnostic marker in colorectal cancer plasma samples." (PMID 32337221, 2020). "OPN expression has been previously shown to enhance colon cancer cell growth, invasion and angiogenesis, and both IGFBP-2 and PF4 have been identified as biomarkers for the early detection of colorectal cancer." (PMID 30538296, 2019). "This study explored the relationships of serum insulin-like growth factors, IGF-I and IGF-II, and their binding proteins (IGFBP)-2 and IGFBP-3, with key clinicopathological parameters in 92 patients with colorectal cancer (cases)." (PMID 11044360, 2000). "log(P/(1-P) = -7.8709 + 4.5956 × IGFBP2 + 0.2732 × ITIH3 + 0.0909 × LRG1 + 0.1015 × C9 -3.2205 × CNDP1 + 0.0239 × ORM1 + 0.0811 × SERPINA1, where P is a value between 0 and 1 that represents the probability of the event (colorectal cancer)." (PMID 38383428, 2024). "Besides, the qRT-PCR experiment confirmed the low expression of IGFBP2 and IGFBP6 in gastric cancer and the low expression of IGFBP6 in colorectal cancer." (PMID 37088808, 2023). "More recently, many studies identified IGFBP2 as an EMT-driver gene that promotes the proliferation and migration of colorectal cancer cells through E-cadherin inhibition or the hepatocellular carcinoma progression by activation of the NF-κB-ZEB1 signaling axis." (PMID 34434494, 2021).
type 2 diabetes (27 papers, 2012 to 2026). "Higher circulating IGFBP-2 concentrations were also longitudinally associated with lower type 2 diabetes risk." (PMID 36970368, 2023). "In 2017, a study revealed possible mechanism by which higher serum IGFBP2 decreases the risk of developing type 2 diabetes." (PMID 33498859, 2021). "As for the IGFBP2 polymorphisms, several studies demonstrated that single nucleotide polymorphisms (SNP) in the IGFBP2 gene are strongly associated with type 2 diabetes." (PMID 33498859, 2021). "Further, several longitudinal studies, meta-analyses and systematic reviews confirmed in different cohorts that IGFBP2 is found decreased in type 2 diabetes and supposes a factor risk for development of type 2 diabetes." (PMID 33498859, 2021). "It was recently reported that higher basal levels of IGFBP-2 were associated with lower risk of metabolic syndrome and type 2 diabetes and its levels increased after bariatric surgery." (PMID 32586279, 2020). "This study reports associations of high baseline IGFBP2 with adverse forward trends in renal function in type 2 diabetes." (PMID 23781310, 2012). "Furthermore, circulating proteins, like ApoF and IGFBP-2, have been associated with non-alcoholic fatty liver disease, a risk factor for type 2 diabetes." (PMID 37889320, 2024). "Reduced IGFBP-2 levels are associated with adiposity, metabolic syndrome, and type 2 diabetes." (PMID 38137505, 2023). "Moreover, low levels of IGFBP2 were described in patients with type 2 diabetes, while higher levels are associated with insulin sensitivity." (PMID 36586437, 2023). "Therefore, there is increasing evidence of the association of polymorphisms of IGFBP2 and type 2 diabetes." (PMID 33498859, 2021). "IGFBP2 is not only associated with type 2 diabetes, but also with gestational diabetes." (PMID 33498859, 2021). "Further, this study provides IGFBP2 as a variable which might be added to improve reliability of the type 2 diabetes cluster with increased risk to develop severe NAFLD." (PMID 32532003, 2020). "In this study, we used ‘real-world’ data to examine the hypothesis that concentrations of IGF2 and IGFBP2 at baseline were associated with longitudinal trends in glomerular filtration rate (GFR) in type 2 diabetes." (PMID 23781310, 2012). "In contrast to the type 2 diabetes patients used as controls, chronic pancreatitis patients exhibited nearly 10-fold higher serum IGFBP-2 levels." (PMID 38137505, 2023). "Odds ratios (ORs) for decreasing values of IGFBP-2, adiponectin and IGFBP-1 measured at baseline and included in the same regression model in the association to development of prediabetes and type 2 diabetes at follow-up in women and men." (PMID 36686443, 2022). "A recent study demonstrates that IGFBP-2 is a predictor of longitudinal deterioration of renal function in type 2 diabetes." (PMID 26858687, 2016). "We found elevated IGFBP2 concentration to be associated with a longitudinal decline in GFR and an increase in proteinuria in Caucasians with type 2 diabetes." (PMID 23781310, 2012). "This study demonstrates that IGFBP2 is a predictor of longitudinal deterioration of renal function in type 2 diabetes." (PMID 23781310, 2012). "In summary, we report that IGFBP2 is a marker for deterioration in renal function in Caucasians with type 2 diabetes." (PMID 23781310, 2012). "In this work, we identify key pathways (e.g., complement cascade), potential therapeutic targets (e.g., FAM3D in type 2 diabetes), and biomarkers of diabetic comorbidities (e.g., EFEMP1 and IGFBP2) through causal inference, pathway enrichment, and Cox regression of clinical trial outcomes." (PMID 40032831, 2025). "As IGFBP2 abundance was already low before the onset of type 2 diabetes in that study, it may probably require further physiological alterations." (PMID 32532003, 2020).
type 2 diabetes (continued). "Finally, when compared to untreated type 2 diabetes patients, the metformin-treated diabetic patients showed increased IGFBP-2 levels with diminished serum IGF-1 levels." (PMID 27009398, 2016). "It is possible that an increase in IGFBP2 concentrations occurs in type 2 diabetes followed by an increase in local IGF1 and IGF2 concentrations in the renal glomerulus, very similar to the hypothesis postulated for IGF1 and IGFBP1 interaction in nephropathy." (PMID 23781310, 2012). "We therefore tested the hypothesis that circulating levels of IGF2 and IGFBP2 predict longitudinal renal function in individuals with type 2 diabetes." (PMID 23781310, 2012). "In addition to IGFBP7 we also found IGFBP2 and 6 to be upregulated in type 2 diabetes." (PMID 39280605, 2024). "While our study was aimed at a population with type 2 diabetes, it would be interesting to study whether the associations of IGFBP2 with eGFR are also true of a non-diabetic study population." (PMID 23781310, 2012). "In obese patients or patients with type II diabetes, circulating IGFBP-2 levels are low, while the overexpression of IGFBP-2 protects against the disease by inhibiting adipogenesis and modulating insulin sensitivity." (PMID 37509659, 2023). "IGFBP2 and IGF2 measurements were performed in 436 individuals (263 males) with type 2 diabetes." (PMID 23781310, 2012). "Here, we study the power of the biomarkers adiponectin, IGFBP-1, IGFBP-2, and also included IGF-I and IGF-II, in predicting prediabetes and type 2 diabetes (T2D) in men and women with normal oral glucose tolerance (NGT)." (PMID 36686443, 2022).